ENSG00000278050
Gene: Miscellaneous RNA gene on chromosome 11 (65,423,638 to 65,423,742, forward strand). Ensembl gene ENSG00000278050.
Gene Ontology:
Cellular component: paraspeckles